PHLPP1 (PH domain and leucine rich repeat protein phosphatase 1)
Diseases named in the same sentence as PHLPP1 in open-access papers (continued):
Sharing a sentence is not in itself a finding about the gene and the disease.
steatosis (1 paper, 2016). Increased lipid within the cytoplasm of cells. "To test whether reduction in hepatic PHLPP2 is sufficient to induce steatosis, we constructed adenoviruses encoding shRNA targeting either Phlpp1 (Ad-shPHLPP1) or Phlpp2 (Ad-shPHLPP2)." (PMID 26743335, 2016).
tumor (75 papers, 2007 to 2025). "Phlpp1 loss alone results only in neoplasia; partial Pten loss is necessary for the development of invasive prostate cancer." (PMID 36358740, 2022). "Our study provides an additional mechanism for PHLPP1 tumor suppressor function where loss of PHLPP1 resulted in multiple mitotic defects that subsequently lead to genomic instability." (PMID 28696259, 2017). "To further establish the role of WDR48 as a tumor suppressor and its dependence on PHLPP1 regulation, we screened for WDR48 mutations in human cancers that might be defective in regulating this pathway." (PMID 24145035, 2013). "Together, these results suggest that WDR48 acts as a potential tumor suppressor by stabilizing PHLPP1, and mutations that disrupt its interaction with substrates may contribute to tumorigenesis." (PMID 24145035, 2013). "The transcription and protein levels of PHLPP1 showed a pronounced decrease in tumor tissues, and this expression level further decreased with age and the malignant progression of the tumor." (PMID 38460947, 2024). "Clinical relevance analysis from the BEST website indicated a noticeable downregulation of PHLPP1 gene expression in tumor tissues." (PMID 38460947, 2024). "Phlpp1 (PH domain and Leucine rich repeat Protein Phosphatase 1), together with Phlpp2, are protein phosphatases that function as tumor suppressors by negatively regulating Akt/PKB, the kinase that integral to PI3K pathway described earlier." (PMID 36358740, 2022). "MiR-199a and miR-375 both target PH Domain And Leucine Rich Repeat Protein Phosphatase 1 (PHLPP1), which acts as a tumor suppressor by downregulating the Akt oncogenic pathway." (PMID 33801049, 2021). "KD of PHLPP1 also partially rescued the number of large tumor spheres and the cell migration in TMEPAI-KO cells." (PMID 34638419, 2021). "PI3K/AKT signaling is well known to be implicated in tumorigenic activities in many types of cancer, and it is already reported that PHLPP1 has a tumor-suppressive role through the negative regulation of PI3K/AKT signaling." (PMID 34638419, 2021). "In another paper, it was reported that the oncosuppressor PHLPP1, known to have an anti-proliferative action on tumor cells, is also involved in the activity of T cells and immune response." (PMID 33672324, 2021). "Phlpp1 functions as a tumor suppressor and is frequently deleted in various cancers, including prostate cancers." (PMID 34575866, 2021). "For instance, tumor malignancy seems to be associated with LAMP-2A overexpression with a poor final prognosis but, at the same time, down-regulation of PHLPP1 has been found in several tumors." (PMID 33672324, 2021). "PHLPP1 is a member of a family of Ser/Thr protein phosphatases (PPases) that serve as tumour suppressors by negatively regulating Akt signaling and its expression is reduced in colorectal cancer." (PMID 29102676, 2018). "In contrast, all the tumor suppressor activities of PHLPP1 have so far been attributed to its role in inhibiting various proliferation and survival signaling pathways." (PMID 28696259, 2017). "PHLPP1 functions as a tumor suppressor by acting on distinct cellular substrates such as Akt, PKC, S6K, RAF1, and Mst1 (7, –, 10)." (PMID 28696259, 2017). "Unfortunately, the genetic loci coding for PHLPP1 and 2 are commonly lost in cancer, and expression of their isoform is also lost or decreased in some tumor tissues." (PMID 27556506, 2016). "PHLPP-1 was discovered to be an Akt phosphatase that selectively dephosphorylates Ser473 on Akt and it was initially confirmed to regulate tumor cell survival." (PMID 27019292, 2016). "It is well known that PHLPP1 being a tumor suppressor promotes apoptosis by negatively regulating Akt." (PMID 24145035, 2013). "Together, our results reveal WDR48 and USP12 as novel PHLPP1 regulators and potential suppressors of tumor cell survival." (PMID 24145035, 2013).
tumor (continued). "Significance: WDR48 was identified as novel PHLPP1 regulator, which is critical in understanding its role as tumor suppressor in human cancers." (PMID 24145035, 2013). "Apart from Akt dephosphorylation, PHLPP1 has additional substrates such as MST1, PKC, and S6K1, which are all critical for PHLPP1 tumor suppressor function." (PMID 24145035, 2013). "We demonstrated that the WDR48·USP12 complex deubiquitinates and regulates PHLPP1 levels, which is essential for their possible tumor suppressor function." (PMID 24145035, 2013). "In our study, in addition to identifying WDR48 as a physical partner of PHLPP1 in cells, functionally we also demonstrated its ability to act as a potential tumor suppressor." (PMID 24145035, 2013). "Since we could not measure any detectable phosphatase activity of PHLPP2, we investigated the evidence for the role of PHLPP1 or PHLPP2 as tumor suppressors." (PMID 40168118, 2025). "Consistent with the lack of somatic mutations in cancer, background mutation rates comparable to olfactory receptor genes, and no patterns of copy number loss in cancer, neither PHLPP1 nor PHLPP2 qualifies as a tumor suppressor." (PMID 40168118, 2025). "Furthermore, as the tumor worsens, there was a further decline in PHLPP1 gene expression, especially during distant metastasis, where this trend became more pronounced." (PMID 38460947, 2024). "The UAF1/USP12 complex deubiquitinates PHLPP1 and suppresses the proliferation of tumor cells." (PMID 36988464, 2023). "Moreover, Western blot analytic data from the tumor tissue samples confirmed the upregulated Ser473 phosphorylation of AKT due to the PHLPP1 KD." (PMID 34638419, 2021). "In addition to the initial inhibitory effect on tumor growth, PHLPP1 has been also found to have a close relationship with myocardial injury in recent years." (PMID 34868398, 2021). "In model systems, Phlpp1 inhibits tumor progression and cancer cell growth." (PMID 34575866, 2021). "Next, we aimed to investigate the effect of PHLPP1 KD on xenograft tumor formation." (PMID 34638419, 2021). "Thus, accumulation of PHLPP1 or DEPTOR upon SAG knockdown plays at least in part a causal role in suppression of tumor cell growth and reverse of tumor cell phenotypes." (PMID 27955654, 2016). "Subsequently, since AKT phosphorylation is negatively regulated by the phosphatase and tensin homolog (Pten) as well as the PH domain and leucine rich repeat protein phosphatase 1 and 2 (Phlpp1 and 2) tumor suppressors, we determined the levels of these proteins by immunohistochemistry." (PMID 25537506, 2015). "We revealed WDR48 as an additional regulator of PHLPP1 and a potential tumor suppressor." (PMID 24145035, 2013). "PHLPP1 acts as a tumor suppressor by negatively regulating the Akt pathway." (PMID 24145035, 2013). "Importantly, we found a WDR48 somatic mutation (L580F) that is defective in stabilizing PHLPP1 in colorectal cancers, supporting a WDR48 role in tumor suppression." (PMID 24145035, 2013). "Given that PHLPP1 acts as a tumor suppressor in various cancers derived from different cellular origins, these regulators may not fully elucidate the molecular players controlling PHLPP1 function." (PMID 24145035, 2013). "Importantly, we found that the genes ranking higher in importance than PHLPP1 were not closely associated with clinical features such as tumor stage and grade." (PMID 38460947, 2024). "PHLPP1 may act as tumor suppressor and AKT phosphorylation regulator in several kinds of tumors." (PMID 35360837, 2022). "PHLPP1 has been proposed as a negative modulator of tumorigenesis, being associated to the promotion of apoptosis and, in U251 cell line, it was demonstrated to be involved in the suppression of tumor malignancy and in the modulation of inflammatory cytokines." (PMID 31653091, 2019). "Thus, WDR48·USP12, being a deubiquitinase complex and a positive regulator of PHLPP1 stability, might function as a tumor suppressor complex as well." (PMID 24145035, 2013).
tumor (continued). "This PH domain is also present in the human PHLPP1 and PHLPP2 phosphatases, which are involved in apoptosis and the suppression of tumour growth." (PMID 38462784, 2024). "A study showed that PKCα was fully phosphorylated at the PHLPP site, and PHLPP1 levels were negatively correlated with PKC in more than 5,000 tumor patients." (PMID 37576883, 2023). "The PHLPP1- and additional genes of the RET signalling pathway were detected in six other primary and relapse tumor samples included in the study." (PMID 36037157, 2022). "It is known that the tumor suppressors PTEN, PP2A, and PHLPP1 can inhibit the activity of the PI3K/AKT pathway." (PMID 34922544, 2021). "PHLPP1 and PHLPP2 have been identified as tumour suppressors because they can suppress of pro‐survival signalling, such as PI3K/Akt signalling pathway." (PMID 31863623, 2020). "Copy losses were also commonly observed for key tumor suppressors relevant to mCRPC biology, including GRHL2, ZFHX3, FGFR2, NCOR1, PHLPP1, and BRCA1." (PMID 31136607, 2019). "Both PHLPP1 and PHLPP2 are tumor suppressors and downregulated in many cancers, thereby maintaining Akt activity as well as promoting proliferation, growth, and survival." (PMID 31027321, 2019). "For example, MicroRNA-30b can function as a tumor suppressor in CRC by targeting KRAS, PIK3CD and BCL2, while MicroRNA-224, a tumor promoter, targets PHLPP1 and PHLPP2, sustains Wnt/β-catenin signaling and promotes aggressive phenotype of CRC." (PMID 29118671, 2017). "In marked contrast, the expressions of PHLPP1 and PHLPP2 were significantly decreased in 83.3% (115/138) and 82.6% (114/138) of tumor tissues, respectively (P<0.0001)." (PMID 25793736, 2015). "Finally, common among these two lists were the tumour suppressor genes DOK2 and PHLPP1 that demonstrated increased gene expression in response to dual inhibition of EZH2 and DNMTs in MM cells and lower expression in MM patient plasma cells compared to NPCs." (PMID 40866476, 2025). "While PHLPP1 and PHLPP2 double knockout mice exhibit only a mild colitis resistance phenotype, their proposed repressive effects on Akt signaling have led to their designation as tumor suppressor genes." (PMID 40168118, 2025). "PHLPP1 is related to the RET signalling pathway and known for the promotion of tumor progression." (PMID 36037157, 2022). "However, the tumor suppressor genes PTEN, PHLPP1, and PP2A all inhibit the activity of the PI3K/AKT pathway." (PMID 34922544, 2021). "Importantly, Western blot analysis of the proteins extracted from the tumor tissues showed higher p-AKT (Ser473) expression in HSP47-overexpressing tumors, whereas the PHLPP1 expression was lower in the same tumors." (PMID 32587773, 2020). "For example, when the tumor suppressor SRPK1 (serine/arginine-rich splicing factor kinase), which mediates the recruitment of the phosphatase PHLPP1 to Akt (besides its role in regulated splicing) was deleted or overexpressed, it resulted in the promotion of cancer." (PMID 30577430, 2018). "Several outlier genes whose knockdown confers striking vulnerability are tumor suppressors including APC, PHLPP1 and SPEN, while a number of other candidates have been reported to harbor anti-oncogenic activities such as the pro-apoptotic gene MTCH2 and the anti-metastatic RNA chaperone RBM47." (PMID 27296290, 2016). "In summary, our data suggest a tumor suppressor role of Xist in inhibiting AKT activation via regulation of non-X-chromosome gene PHLPP1 expression." (PMID 27248326, 2016). "However, the expressions of PHLPP1 and PHLPP2 were significantly decreased in 83.3% (115/138) and 82.6% (114/138) of tumor tissues, respectively (P<0.0001, both)." (PMID 25793736, 2015). "In an attempt to identify molecular players involved in regulation of PHLPP1 during its tumor suppressor function, we transfected 293T cells with a triple epitope (S-protein, FLAG, and streptavidin-binding peptide)-tagged version of PHLPP1 (SFB-PHLPP1)." (PMID 24145035, 2013).
tumor (continued). "Furthermore, we found that cancer genomics data do not support the proposed role of PHLPP1 or PHLPP2 as tumor suppressors." (PMID 40168118, 2025). "Although PHLPP1 KD did not bring about full recovery of tumor growth in TMEPAI-KO MDA-MB 231 cells, we hypothesize that it is probably due to the tumorigenic function of TMEPAI through SIM-mediated signal regulation and/or suppression of PTEN." (PMID 34638419, 2021). "It was PHLPP1 but not PHLPP2 that was significantly related to the tumor T stage (P = 0.047)." (PMID 25793736, 2015). "It was PHLPP1 but not PHLPP2 that was significantly related to the tumor T stage." (PMID 25793736, 2015). "High levels of PHLPP1 (but not PHLPP2), with corresponding low phosphorylation levels of Akt2 (but not Akt1) regulates pancreatic cell death and tumor formation." (PMID 36376971, 2022). "So, the expressions of both PHLPP1 and PHLPP2 mRNAs in tumor samples were much lower than in adjacent nontumor mucosae." (PMID 25793736, 2015). "PHLPP1 and PHLPP2 mRNA transcript levels were significantly lower in tumor samples than in paired adjacent nontumor mucosae (P<0.0001, both)." (PMID 25793736, 2015). "At that time, there was no research that unveiled the specific role of PHLPP1 in KIRC, but based on existing results, we speculated that it might have exerted anti-tumor effects by inhibiting tumor proliferation, migration, and invasion." (PMID 38460947, 2024).
cancer (66 papers, 2012 to 2025). A tumor composed of atypical neoplastic, often pleomorphic cells that invade other tissues. "In summary, there is scant evidence from disease genotypes, clinically reported variants, or GWASs to support that dysregulation of either PHLPP1 or PHLPP2 is associated with cancer." (PMID 40168118, 2025). "Among them, PHLPP1, a tumor suppressor gene for various cancer types, has the second highest mutation frequency in PTMETA (12.5%)." (PMID 36941725, 2023). "The loss of PHLPP1 is reported in various cancers such as colon, breast, ovarian, Wilms tumors, prostate, and hepatocellular carcinomas." (PMID 24145035, 2013). "In turn, the PH domain leucine-rich repeat protein phosphatases (PHLPP1 and PHLPP2) dephosphorylate AKT on its hydrophobic motif (Ser473 in humans), whereby the loss of PHLPP activity, which appears to frequently occur in cancer, results in AKT hyperphosphorylation." (PMID 29610153, 2018). "In the future it would be very interesting to screen different human cancers for additional WDR48 mutations that might not only be defective in maintaining PHLPP1 function but also other substrates such as BRCA1, FANCD2, H2A/H2B, PCNA, and notch receptor." (PMID 24145035, 2013). "Moreover, the phosphorylated S473 residue on Akt is dephosphorylated by the two isoforms of PHLPP (1 and 2) Decreased PHLPP activity has been linked to specific types of cancers." (PMID 23006971, 2012). "However, PHLPP1 inactive mutation in cancer cells has rarely been reported." (PMID 34638419, 2021). "There were also significant inverse correlations between BMI-1 and PHLPPs, especially PHLPP1, in normal and cancer endometrial tissue samples." (PMID 36497428, 2022). "Several studies reported that inactivation of AKT Ser473 by PHLPP1 suppresses tumorigenicity in cancer cells." (PMID 34638419, 2021). "Akt phosphorylation itself is regulated by PHLPP1 and PHLPP2 phosphatases, and their impaired function is linked to cancer." (PMID 31027321, 2019). "Although genetic ablation of either or both genes in mice is not lethal and results in no reported predisposition to cancer, an evolutionary pressure of some sort has retained both PHLPP1 and PHLPP2 in vertebrates." (PMID 40168118, 2025). "Similarly, a recent study revealed that either overexpression or knockdown of SRPK1 decrease the association between Akt and PHLPP1 and then interfere with PHLPP-mediated dephosphorylation of Akt, resulting in the promotion of cancer." (PMID 32989053, 2020). "In summary, our results for the first time showed that down‐regulation of BMI‐1 in cancer cells might affect expression of PHLPP1 and PHLPP2." (PMID 31863623, 2020). "PTEN-deficient neurons exhibit seizures, autism-related disorders, and are highly prone to cancer, which do not emerge in Phlpp1-deficient mice." (PMID 31582730, 2019). "Also, whole body SCOP/PHLPP1 KOs are the most widely studied of the various strains and have been investigated in the setting of cancer, immunity, cardiovascular disease, and in stroke." (PMID 29739983, 2018). "Also, PHLPP1 levels are markedly reduced in several cancer cell lines that have elevated Akt phosphorylation, and the reintroduction of PHLPP1 reduces cell growth by inactivating the Akt pathway." (PMID 24145035, 2013). "Additionally, it was reported that PHLPP1 acts as a tumor suppressor in cancer cells." (PMID 39863100, 2025). "Although the upstream pathway of AKT is frequently activated in cancer cells, owing to receptor and PI3K activation or PTEN inactivation, PHLPP1 suppresses AKT signaling by specific dephosphorylation of AKT Ser473." (PMID 34638419, 2021). "In addition, SRPK1 promotes cancer by regulating AKT phosphatase to induce AKT dephosphorylation by interacting with PHLPP1, which could dephosphorylate p-AKT, lead to AKT constitutive activation suggesting that SRPK1 plays a key role in signaling transduction." (PMID 34193174, 2021).